GPC3 (glypican 3)
Diseases named in the same sentence as GPC3 in open-access papers (continued):
Sharing a sentence is not in itself a finding about the gene and the disease.
hepatocellular carcinoma (continued). "Another recent study has documented that Glypican-3 (GPC3) is targeted by miR-4510 in liver malignancies; including hepatocellular carcinoma (HCC) and hepatoblastoma." (PMID 36755123, 2023). "GPC3 is highly expressed in 70–100% of hepatocellular carcinomas (HCC)." (PMID 37048069, 2023). "GPC3-induced ERK activation promotes EMT and enhances cell migration and invasion in hepatocellular carcinoma." (PMID 36358747, 2022). "For example, the hepatocellular carcinoma (HCC) microenvironment is devoid of interleukin (IL) 15 and 21, which are essential for the proper functioning of T-cells, therefore human GPC3-CAR T cells co-expressing IL-15 and IL-21 were very efficient in the treatment of HCC in preclinical models." (PMID 36428480, 2022). "Clinical trials have evaluated that glypican-3 (GPC3), a tumor-specific antigen, is expressed in all hepatocellular cancers." (PMID 35686237, 2022). "Another potential antigen target in hepatocellular carcinoma (HCC) for CAR T is glypican‐3 (GPC3)." (PMID 35844304, 2022). "Glypican-3 (GPC3) is a membrane-associated proteoglycan that is specifically up-regulated in hepatocellular carcinoma (HCC) although rarely or not expressed in normal liver tissues, making it a perfect diagnostic and treatment target for HCC." (PMID 35251989, 2022). "As a regulator of the oncofoetal genes alpha foetal protein (AFP) and glypican-3 (GPC3), ZHX2 inhibits the development of hepatocellular carcinoma." (PMID 35151335, 2022). "A human monoclonal antibody against the GPC3 HS chain inhibited HGF/c-Met pathway-mediated migration and motility in hepatoma cells." (PMID 35251989, 2022). "Here, we performed a phage-displayed bio-panning to identify a specific binding peptide targeting Glypican-3 (GPC-3), a promising biomarker in hepatocellular carcinoma (HCC)." (PMID 34150644, 2021). "Indeed, GPC-3 positive immunostaining can differentiate hepatocellular carcinoma (HCC) from dysplastic changes in cirrhotic livers." (PMID 33450845, 2021). "In hepatocellular carcinoma (HCC) cells and mouse models, researchers identified the Wnt binding domain on glypican-3 as being a phenylalanine 41 residue in the hydrophobic groove in the N-lobe and both the core protein and HS chains can activate Wnt-β-catenin signalling." (PMID 33561383, 2021). "Importantly, GPC3 is highly represented in over 70% of hepatocellular carcinoma (HCC), which is one of the most prevalent cancers worldwide." (PMID 34922633, 2021). "We found the co-expression of TFPI and GPC3 on the surface of CLL cells and co-IP confirmed the binding between the two proteins, which is consistent with previous studies on the hepatocellular carcinoma cell line HepG233 and hematopoietic stem cells." (PMID 33664415, 2021). "Our study showing Glypican-3 expression in both UESL and HMH cases demonstrates that this marker cannot be used to differentiate the two from hepatocellular carcinoma and hepatoblastoma which have been shown to express this antigen." (PMID 34162402, 2021). "For instance in hepatocellular carcinoma (HCC), an overexpression of glypican-3 increases the migratory ability and invasive capacity of cancer cells by reducing cell adhesion to fibronectin whereas it plays an inhibitory role in breast cancer." (PMID 33742285, 2021). "Szoor and colleagues used MSCs that expressed GPC3-specific single-chain variable fragment (scFv) and CD3-specific scFv (MSCGPC3-CD3) to direct GPC3-specific CD4+ T helper cells and CD8+ CTLs towards the GPC3-expressing hepatocellular carcinoma cells." (PMID 34830312, 2021). "In the same line, in hepatocellular carcinoma, the strategies of immunotoxin and CAR-T cells against GPC3 are showing promising results and are under clinical trials." (PMID 33494442, 2021). "Here, we constructed sorafenib-loaded polyethylene glycol-b-PLGA polymer nanoparticles modified with antibody hGC33 to glypican-3 (GPC3 +), a membrane protein overexpressed in hepatocellular carcinoma." (PMID 33242103, 2020).
hepatocellular carcinoma (continued). "Glypican-3 is a highly sensitive biomarker of hepatocellular carcinoma (HCC)." (PMID 33371487, 2020). "Another interesting proteoglycan for clinical purposes is glypican-3 (GPC3), which is upregulated amongst several cancer entities with highest positive case rates in hepatocellular carcinoma (HCC)." (PMID 32984308, 2020). "Increased level of GPC3 in serum could serve as a marker for hepatoblastoma as well as hepatocellular carcinoma (HCC)." (PMID 33302876, 2020). "CAR-T cells against tumor-specific antigens (TSA), including mesothelin (MSLN) and glypican 3 (GPC3) are being actively tested for treating non-small-cell lung cancer (NSCLC) and hepatocellular carcinoma, respectively." (PMID 32514352, 2020). "GPC3 is overexpressed in some kinds of tumors, particularly hepatocellular carcinoma (HCC)." (PMID 31510063, 2019). "In the JM2 rat hepatoma cell line, forced expression of CD81 in the presence of high GPC3 expression, increased activation of the Hippo pathway by decreasing nuclear YAP." (PMID 31428581, 2019). "Therefore, in our study, we built synNotch receptors capable of recognizing glypican-3(GPC3) which demonstrated to be highly expressed in hepatocellular carcinoma (HCC)." (PMID 31921693, 2019). "The cell surface heparan sulfate proteoglycan Glypican-3 (GPC3) is a serological and histochemical marker of hepatocellular carcinoma (HCC), due to its high and specific expression in HCC." (PMID 30922327, 2019). "Glypican 3 (GPC3) is highly expressed in hepatocellular carcinoma (HCC) and hepatoblastoma." (PMID 28356156, 2017). "We constructed a Plasmodium yoelii 17XNL strain (P.y) expressing murine glypican-3 (GPC3) protein (P. y-GPC3), and examined its therapeutic potency in a murine Hepa1-6-induced hepatoma model that highly expressed GPC3 protein." (PMID 28445973, 2017). "Background/Objectives: Glypican-3 (GPC3) is a cell surface oncofetal protein that is highly expressed in hepatocellular carcinoma (HCC) but absent in normal liver tissue, making it an attractive target for molecularly targeted diagnosis and therapy." (PMID 41154412, 2025). "Examples include targeting EGFR and c-Met in NSCLC or GPC3 and MUC13 in hepatocellular carcinoma." (PMID 41348261, 2025). "Glypican 3 (GPC3) is highly expressed in most hepatocellular carcinomas (HCCs) but is absent in normal adult liver tissue." (PMID 41463223, 2025). "Glypican 3 (GPC3) is one such protein found at elevated levels in more than 70% of hepatocellular carcinoma (HCC) cases, while it is nearly absent in normal tissues." (PMID 40308592, 2025). "Background/Objectives: The cell surface proteoglycan glypican-3 (GPC3) is reportedly overexpressed in hepatocellular carcinoma (HCC) tissues, but not in benign liver tissues, rendering this protein a potential target for radionuclide theranostic approaches." (PMID 41304901, 2025). "Additionally, GPC3-specific CAR-T cells engineered with IL-21 and CXCL9, combined with PD-1 blockade, have enhanced cytotoxic capabilities against hepatocellular carcinoma." (PMID 40308592, 2025). "Therefore, a phase I clinical trial was initiated in which GPC3-7-19 CAR T cells showed good safety and anti-tumour efficacy in patients with hepatocellular carcinoma (HCC)." (PMID 38675377, 2024). "These tumors were diagnosed as hepatocellular carcinoma with the expression of GPC3 and EPCAM, but lacking MYC overexpression." (PMID 39529166, 2024). "Glypican-3 (GPC3)-targeted radioisotope immuno-positron emission tomography (immunoPET) may lead to earlier and more accurate diagnosis of hepatocellular carcinoma (HCC), thus facilitating curative treatment, decreasing early recurrence, and enhancing patient survival." (PMID 38978570, 2024). "Both GPC3 and B7H3 are strongly expressed antigens in hepatocellular carcinoma." (PMID 39711794, 2024).
hepatocellular carcinoma (continued). "Expression of GPC3 has been found in hepatocellular carcinoma by several authors; it was found to be absent or expressed at a low level in healthy liver or benign liver diseases." (PMID 38727261, 2024). "GPC-3 is not expressed in normal or cirrhotic liver tissue but is overexpressed in hepatocellular carcinoma (HCC)." (PMID 37446098, 2023). "Notably, it is important to distinguish an EGCT from hepatocellular carcinoma, hepatocellular carcinoma cells can also express AFP and glypican-3." (PMID 37138865, 2023). "In the HepG2 cell line, SFB-loaded polymer NPs modified with an anti-GPC3 antibody (NP-SFB-Ab) exhibited higher cellular uptake, better stability, a higher concentration of SFB in the cell culture medium, and higher cytotoxicity to hepatoma cells." (PMID 35248060, 2022). "Other studies proved the effectiveness of CAR-T cells targeting glypican-3 (GPC3), which is present in hepatocellular carcinoma (HCC) but not on normal liver tissue." (PMID 36428480, 2022). "Studies have revealed that GPC3 is not expressed in normal tissues while is highly expressed in many cancer cells, especially showing a close relation with hepatocellular carcinoma (HCC)." (PMID 34261411, 2021). "By interrogating GEO datasets, the authors found that DUSP9 transcript (along with Glypican-3 and α-fetoprotein) was overexpressed in HCCs, fetal livers and human hepatoma cell lines compared to their corresponding non-tumoral counterparts." (PMID 34768967, 2021). "GPC-3–targeted CAR T cells in murine models of hepatocellular carcinoma showed potent antitumor activity without any significant toxicities, while also targeting soluble GPC-3 antigens." (PMID 34760690, 2021). "Glypican-3 (GPC3) is expressed in 75% of hepatocellular carcinoma (HCC), but not normal liver, making it a promising HCC therapeutic target." (PMID 33374953, 2020). "Similarly, Glypican-3 was suggested as CAR-T-cell target for melanoma, lung and hepatocellular carcinoma, respectively." (PMID 33330449, 2020). "Because the tumorwas also negative for the biomarker glypican-3, well-differentiated hepatocellular carcinoma wasexcluded, and the patient was finally diagnosed with HCA." (PMID 35111517, 2020). "However, GPC3 protein is overexpressed in about 70% of hepatocellular carcinoma (HCC) patients and stimulates classic Wnt signal transduction through interaction with Wnt ligand, which promotes Wnt/frizzled binding to promote HCC growth." (PMID 33242103, 2020). "Recently, a study showed that GPC3-targeted CAR T cells could eliminate orthotopic and xenograft hepatocellular carcinomas in vitro and in vivo." (PMID 32942580, 2020). "Earlier studies suggested that Glypican-3 is an important liver cancer specific target, as it is highly expressed in hepatocellular carcinoma but not in normal tissue." (PMID 33126630, 2020). "The utility of glypican-3 (GPC3) expression for the detection of circulating tumor cells (CTCs) in hepatocellular carcinoma (HCC) patients has not been elucidated." (PMID 31141571, 2019). "It was proposed that GPC3 could interact with CD16/FcγRIIIa and trigger antibody-dependent cytotoxicity in hepatocellular carcinoma cells." (PMID 28510121, 2017). "The significant increases in expression of GPC3 in hepatocellular carcinoma and ARDS raise the question whether GPC3 has utility as a biomarker of disease or disease severity." (PMID 28510121, 2017). "In this TDCC assay, the effector cells were spleen cells of human CD3 EDG–replaced mice and the target cells were Hepa1-6/hGPC3/HER2 cells, in which human glypican-3 (GPC3) and erb-b2 receptor tyrosine kinase 2 (HER2) are significantly expressed in Hepa1-6 mouse hepatocellular carcinoma." (PMID 28368009, 2017). "Conversely, the expression of this glypican is up-regulated in hepatocellular carcinomas, although Glypican-3 is not expressed in the liver, suggesting that in this case it behaves as an oncofoetal protein." (PMID 26517809, 2015).
hepatocellular carcinoma (continued). "Immunohistochemical analysis has shown that tumor cells in gynecological cancer tissues stain positive for CK7 and negative for CK20, while glypican-3 is generally positive in hepatocellular cancer and renal cell cancer." (PMID 25530894, 2014). "As opposed to the results of this study in clear cell renal cell carcinoma, GPC3 overexpression has emerged as a positive marker in liver cancer because it is highly expressed in 70-100% of hepatocellular carcinomas (HCCs) but not in normal adult liver tissue." (PMID 25168166, 2014). "GPC3 modulates the effect of growth factors such as IGF-2, BMP-7 and FGF-2 on hepatoma cells and may recruit M2 tumor-promoting macrophages to the HCC microenvironment." (PMID 22564378, 2012). "In addition, using hepatocellular carcinoma PDXs and lung cancer cases 1 and 2 PDXs, we established a system for simultaneously staining five membrane protein common cancer antigens EphB4, ROBO1, LAT1, CLDN1, GPC3, and HLA class I in six colors." (PMID 40076777, 2025). "Positron emission tomography (PET) imaging targeting glypican-3 (GPC3) holds promise for improving the detection and characterization of hepatocellular carcinoma (HCC)." (PMID 40722645, 2025). "For instance, CAR-Ms targeting Glypican-3 (GPC3) are adept at recognizing and eliminating hepatocellular carcinoma (HCC) cells due to their antigen-specific recognition domains on the cell surface." (PMID 40308592, 2025). "Similarly, a logic-gated GPC3 Syn/notch receptor was used to control the expression of a CAR targeting CD147 in a hepatocellular carcinoma model, leading to the specific killing of GPC3 + CD147+ cells but not single antigen-positive cells." (PMID 38443448, 2024). "NCT03198546 is a phase 1 trial testing the safety and efficacy of anti-GPC3-7 × 19 CAR-T cells (GPC3 CAR-T cells to secrete human IL-7 and CCL19) in patients with advanced hepatocellular carcinoma (HCC) expressing GPC3." (PMID 37371075, 2023). "Glypican-3 is only greatly expressed in non-cirrhotic hepatocellular carcinoma cases." (PMID 37305177, 2023). "Our previous studies established a series of immunotoxins targeting glypican-3 (GPC3), a cell surface antigen that is specifically expressed in hepatocellular carcinoma (HCC)." (PMID 37626430, 2023). "GPC3 knockdown-mediated cell cycle inhibition could be recapitulated with the addition of human recombinant TGF-β2, suggesting the possible involvement of TGF-β2 in the growth inhibition of hepatocellular carcinoma cells." (PMID 38067167, 2023). "Furthermore, IL-15 and IL-21 armored anti-GPC3 CAR-T cells have progressed to several ongoing phase I clinical trials against GPC3 + pediatric solid tumors (NCT04377932, NCT04715191), hepatocellular carcinoma (NCT05103631), neuroblastoma (NCT03721068), and osteosarcoma (NCT03721068)." (PMID 36167831, 2023). "studied, in vitro and in vivo, the ability of GPC3 (Glypican 3 protein)-targeted CAR-T cells co-expressing IL-7 and the PH20 hyaluronidase to infiltrate hepatocellular carcinoma (HCC) xenograft models." (PMID 35211124, 2022). "In the present study, we observed that serum values of five biomarkers (namely, AFP, PIVKA-II, GPC-3, adiponectin and IL-6) were significantly different between patients with and without hepatocellular carcinoma; the best accuracy for the detection of tumor was achieved by PIVKA-II." (PMID 34064999, 2021). "An increased activation of GPC3-specific T cells and significantly reduced hepatocellular carcinoma growth were observed in MSCsGPC3-CD3-treated tumor-bearing mice, demonstrating the therapeutic potential of MSCsGPC3-CD3 in the immunotherapy of hepatocellular carcinoma." (PMID 34830312, 2021). "In another study, CXCR2-expressing anti-glypican-3 (GPC3)-CAR-T cells showed improved migration and activity in a xenograft hepatocellular carcinoma (HCC) tumour model." (PMID 32722109, 2020).
hepatocellular carcinoma (continued). "Consequently, GPC3 has a high tumor specificity due to its upregulation in hepatocellular carcinoma and lack of expression in healthy human tissues." (PMID 32575752, 2020). "The virtually negative AFP does not rule out a YST, while expression of glypican-3 can be found in various somatic tumor types such as hepatocellular carcinoma, hepatoid carcinoma, neuroendocrine carcinoma, thyroid carcinomas, lung carcinoma, liposarcoma, and melanoma." (PMID 32774158, 2020). "GPC3 is expressed in 95% of hepatocellular carcinomas, but not in neuroendocrine tumor metastatic to the liver, and cholangiocarcinoma, measured by liver cancer tissue microarrays which were constructed from hepatocellular carcinoma, neuroendocrine tumor, and cholangiocarcinoma samples." (PMID 28510121, 2017). "We found that glypican-3 (GPC3), which is an oncofetal antigen that is overexpressed in human hepatocellular carcinoma (HCC), was shown to be a useful target antigen for immunotherapy in several studies." (PMID 25189159, 2014). "Glypican-3 (GPC3) is specifically expressed in ovarian clear cell carcinoma (OCCC), hepatocellular carcinoma (HCC), and melanoma and lung cancer." (PMID 24992906, 2014). "However, the effect of the downregulation of GPC-3 expression on hepatoma cell proliferation was still not clearly defined." (PMID 23192642, 2013). "Glypican-3 (GPC3), which is a carcinoembryonic antigen, is overexpressed in human hepatocellular carcinoma (HCC)." (PMID 23903757, 2013). "Glypican-3 (GPC3)-specific CAR-NK-92 cells have been also explored, demonstrating potent antitumor effects both in vitro and in vivo against hepatocellular carcinoma (HCC)." (PMID 40519903, 2025). "Glypican-3 (GPC3), previously called MRX7, is a membrane-associated heparan sulfate proteoglycan that is up-regulated in hepatocellular carcinoma (HCC), especially in poorly-differentiated subsets, with absent or scarce expression in normal liver tissue." (PMID 39267840, 2024). "GPC3 is overexpressed in Hepatocellular carcinoma (HCC) tissues, but not in the liver of healthy adults." (PMID 37919282, 2023). "GPC3 is an interesting target for hepatocellular carcinoma (HCC) patients, because it is highly expressed in HCC, while it is not expressed in normal tissues." (PMID 35453596, 2022). "In a preclinical model of hepatocellular carcinoma (HCC), these inducible IL-12 Glypican-3 CARs significantly improved survival of mice compared to non-IL-12-secreting Glypican-3 CARs." (PMID 34868044, 2021). "Therefore, a potential target of GPC3 on hepatocellular carcinoma for extravascular targeted imaging may not be realized in contrast-enhanced ultrasound." (PMID 33354418, 2020). "Increased tumor GPC3 expression was more commonly reported in a study of women than men with hepatocellular carcinoma (HCC), the most common adult liver tumor, although this has not been reproduced in subsequent studies." (PMID 30873384, 2019). "Glypican-3 (GPC3) is overexpressed in human hepatocellular carcinoma (HCC) but not expressed in normal tissues except for placenta and fetal liver and therefore is an ideal target for cancer immunotherapy." (PMID 23354275, 2013). "In tissues with no adult expression, GPC3 may act as an oncofetal protein, and tumors derived from these tissues have increased levels of GPC3 mRNA (hepatocellular carcinoma, hepatoblastoma, Wilms tumor, neuroblastoma, and rhabdomyosarcoma), with protein studies limited to the first three." (PMID 20868507, 2010). "Glyican-3 (GPC3) is a GPI-anchored cell surface oncofetal proteoglycan which is overly expressed in fetal liver and hepatocellular carcinoma (HCC) but not in normal liver." (PMID 40565299, 2025). "Glypican-3 (GPC3) is a surface biomarker expressed on HCC cells and is a therapeutically attractive target since its expression is predominantly high in hepatocellular carcinoma (HCC) and not in healthy cells." (PMID 40746528, 2025).